ENKUR (enkurin, TRPC channel interacting protein)
Description:
Adapter that functions to localize a calcium-sensitive signal transduction machinery in sperm to a calcium-permeable ion channel (By similarity). Microtubule inner protein (MIP) part of the dynein-decorated doublet microtubules (DMTs) in cilia axoneme, which is required for motile cilia beating.
Synonyms: C10orf63; MGC26778; enkurin; CFAP106
Tractability: Small molecule: a structure with a bound ligand is known.
Gene: Protein-coding gene on chromosome 10 (24,981,979 to 25,062,279, reverse strand). Ensembl gene ENSG00000151023.
Subcellular location: Cytoplasm, cytoskeleton, cilium axoneme; Cytoplasm, cytoskeleton, flagellum axoneme
Subcellular location (Human Protein Atlas): Mid piece; Cytosol; Principal piece
Gene Ontology:
Molecular function: protein binding; calmodulin binding
Biological process: establishment of left/right asymmetry; flagellated sperm motility
Cellular component: 9+2 motile cilium; axonemal microtubule; sperm midpiece; sperm principal piece; acrosomal vesicle; axonemal B tubule inner sheath; sperm flagellum; 9+0 motile cilium; axoneme; cilium; microtubule cytoskeleton
Genetic constraint (gnomAD): Loss-of-function variants: 19 observed, 28.44 expected, observed/expected ratio (o/e) 0.67, 90% interval 0.47 to 0.98. The upper end of that interval is the gene's LOEUF score, 0.98, which puts it in group 4 of 6, group 1 being the genes least tolerant of losing a copy. Missense variants: 312 observed, 323.81 expected, observed/expected ratio (o/e) 0.96, 90% interval 0.88 to 1.06. Synonymous variants: 117 observed, 100.94 expected, observed/expected ratio (o/e) 1.16, 90% interval 1 to 1.35.
Homologues: Orthologues: chimpanzee ENKUR (99% identical), macaque ENKUR (95% identical), pig ENKUR (89% identical), dog ENKUR (88% identical), mouse Enkur (87% identical), guinea pig ENKUR (86% identical), rat Enkur (85% identical), rabbit ENKUR (68% identical), tropical clawed frog enkur (58% identical), zebrafish enkur (57% identical), Drosophila melanogaster CG16984 (32% identical). Paralogues in human: ENKD1 (16% identical).
Diseases named in the same sentence as ENKUR in open-access papers:
ENKUR is named in the same sentence as 16 diseases in open-access papers, as found by Europe PMC text mining. Sharing a sentence is not in itself a finding about the gene and the disease. The quoted sentences say what the papers report.
lung adenocarcinoma (2 papers, 2019 to 2022). A carcinoma that arises from the lung and is characterized by the presence of malignant glandular epithelial cells. "Previous studies had showed that ENKUR is a potential tumor suppressor participating the pathogenesis of lung adenocarcinoma and colorectal cancer cells 12,13." (PMID 35414777, 2022).
situs inversus (2 papers, 2020 to 2022). A congenital condition in which there is complete right-to-left reversal of the position of the major thoracic and abdominal organs (that is, they are arranged in a mirror image of the normal positioning). "In addition, mutations in ENKUR is linked to situs inversus in human and mouse." (PMID 31951202, 2020).
colon adenocarcinoma (1 paper, 2019). "Compared with normal tissues, ENKUR was significantly down-regulated by approximately 50% in LAD as well as in colon adenocarcinoma, kidney chromophobe, lung squamous cell carcinoma, and thyroid carcinoma (p<0.05)." (PMID 31417642, 2019).
Infertility (1 paper, 2023). "Some genes with lower expression levels, namely DPCD, NME8, and ENKUR, had not yet been clearly related to biological functions in sperm production, function, and/or infertility-related manifestations." (PMID 37174638, 2023).
male infertility (1 paper, 2024). The inability of the male to effect fertilization of an ovum after a specified period of unprotected intercourse. "Lately, several genes have been reported to be associated with laterality defects, male infertility, and mild variable respiratory phenotypes such as CCDC11/CFAP53, ENKUR, WDR16/CFAP52, DAW1, and MNS1." (PMID 38920647, 2024).
Situs inversus totalis (1 paper, 2020). "Loss-of-function mutations in CFAP52 and ENKUR cause situs inversus totalis in humans; ENKUR-deficient individuals show respiratory ciliary beating within normal range and do not fulfill diagnostic criteria for PCD29." (PMID 33139725, 2020).
tumor (4 papers, 2016 to 2025). "Collectively, these findings suggest that ENKUR (as a tumor suppressor) is involved in the pathogenesis of EC." (PMID 39990660, 2025). "We also established a subcutaneous xenograft tumor model in nude mice to further verify the role of ENKUR in vivo." (PMID 39990660, 2025). "In the present study, we detected the expression of ENKUR in EC, and evaluated its tumor suppressor role in human EC cells and nude mice." (PMID 39990660, 2025). "Our data demonstrated that ENKUR induced by CB suppresses HCC malignant activities via antagonizing β-catenin/c-Jun/MYH9/USP7/c-Myc-stimulated cell cycle and EMT pathways, which indicated the significance of ENKUR as a tumor suppressor in HCC." (PMID 35414777, 2022). "As a result, the interaction between ENKUR and β-catenin is increased to antagonize β-catenin-stimulated tumor growth and EMT signals." (PMID 35414777, 2022). "Subsequently, we confirmed that CB induced ENKUR levels through downregulating PI3K/AKT/c-Jun axis, which thus increased ENKUR/β-catenin complex formation and finally modulated β-catenin-related tumor growth and EMT signals." (PMID 35414777, 2022). "We also investigated the effects of aberrant ENKUR expression on the biological behavior and tumor-forming ability of LAD cells and revealed potential involvement of ENKUR in the MAPK/ERK and PI3K/Akt signaling pathways." (PMID 31417642, 2019). "Next, we explored the expression of ENKUR mRNA in human tumor tissues using Oncomine, a cancer microarray database, which provides access to a large collection of cancer profiling datasets and analytical tools." (PMID 31417642, 2019). "Significant down-regulated ENKUR expression was observed in clinical tumor tissues of LAD as well as in human LAD cells." (PMID 31417642, 2019). "Meanwhile, the expression level of ENKUR was lower in tumor tissues with higher pathological stage (p < 0.05)." (PMID 31417642, 2019). "The present data are the first to demonstrate that ENKUR is a tumor suppressor in EC, and may be an important target for EC therapy." (PMID 39990660, 2025). "Moreover, silencing of ENKUR increased cell proliferative, migratory, and invasive properties in vitro and promoted tumor growth in vivo." (PMID 31417642, 2019). "Furthermore, ENKUR also binds to E3 ligase F-box and WD repeat domain containing 7 (FBXW7), a critical tumor suppressor." (PMID 39990660, 2025).
cancer (2 papers, 2019 to 2022). A tumor composed of atypical neoplastic, often pleomorphic cells that invade other tissues. "Here, ENKUR was significantly downregulated in HCC compared with the para-cancer tissues, indicating that ENKUR expression is an independent predictive factor for the outcome of HCC patients." (PMID 35414777, 2022).
ENKUR also shares sentences with these, for which no sentence is quoted: colorectal cancer (1 paper); Crohn disease (1); hematological cancers (1); hepatocellular carcinoma (1); lung carcinoma (1); lung squamous cell carcinoma (1); nasopharyngeal carcinoma (1); thyroid carcinoma (1).